PREX1 (phosphatidylinositol-3,4,5-trisphosphate dependent Rac exchange factor 1)
Description:
Functions as a RAC guanine nucleotide exchange factor (GEF), which activates the Rac proteins by exchanging bound GDP for free GTP. Its activity is synergistically activated by phosphatidylinositol 3,4,5-trisphosphate and the beta gamma subunits of heterotrimeric G protein. May function downstream of heterotrimeric G proteins in neutrophils.
Synonyms: P-Rex1; KIAA1415
Tractability: Antibody: its Gene Ontology location is reachable by antibodies, with high confidence; UniProt places it where antibodies can reach, with medium confidence. PROTAC: ubiquitination databases record sites on it; its protein half-life has been measured.
Gene: Protein-coding gene on chromosome 20 (48,624,249 to 48,828,096, reverse strand). Ensembl gene ENSG00000124126.
Subcellular location: Cytoplasm, cytosol; Cell membrane
Subcellular location (Human Protein Atlas): Cytosol; Vesicles
Pathways (Reactome):
Signal Transduction: CDC42 GTPase cycle; G alpha (12/13) signalling events; NRAGE signals death through JNK; RAC1 GTPase cycle; RAC2 GTPase cycle; RAC3 GTPase cycle; RHOA GTPase cycle; RHOB GTPase cycle; RHOC GTPase cycle; RHOG GTPase cycle; RHOJ GTPase cycle; RHOQ GTPase cycle
Gene Ontology:
Molecular function: phospholipid binding; protein binding; enzyme binding; GTPase activator activity; guanyl-nucleotide exchange factor activity; protein serine/threonine kinase inhibitor activity
Biological process: actin filament polymerization; G protein-coupled receptor signaling pathway; negative regulation of TOR signaling; neutrophil activation; regulation of small GTPase mediated signal transduction; superoxide metabolic process; intracellular signal transduction; leukocyte activation; positive regulation of cell migration; reactive oxygen species metabolic process; regulation of actin filament polymerization; regulation of dendrite development
Cellular component: cytosol; plasma membrane; dendritic shaft; growth cone; perinuclear region of cytoplasm
Genetic constraint (gnomAD): Loss-of-function variants: 40 observed, 194.12 expected, observed/expected ratio (o/e) 0.21, 90% interval 0.16 to 0.27. The upper end of that interval is the gene's LOEUF score, 0.27, which puts it in group 1 of 6, group 1 being the genes least tolerant of losing a copy. Missense variants: 1,610 observed, 2,184.4 expected, observed/expected ratio (o/e) 0.74, 90% interval 0.71 to 0.77. Synonymous variants: 840 observed, 880.25 expected, observed/expected ratio (o/e) 0.95, 90% interval 0.9 to 1.01.
Homologues: Orthologues: chimpanzee PREX1 (99% identical), macaque PREX1 (99% identical), pig PREX1 (92% identical), mouse Prex1 (90% identical), rat Prex1 (90% identical), guinea pig PREX1 (90% identical), rabbit PREX1 (82% identical), dog PREX1 (79% identical), tropical clawed frog prex1 (77% identical), zebrafish prex1 (67% identical). Paralogues in human: PREX2 (56% identical), GPR155 (9% identical), DEPTOR (8% identical).
Diseases named in the same sentence as PREX1 in open-access papers:
PREX1 is named in the same sentence as 59 diseases in open-access papers, as found by Europe PMC text mining. Sharing a sentence is not in itself a finding about the gene and the disease. The quoted sentences say what the papers report.
breast cancer (27 papers, 2011 to 2025). A primary or metastatic malignant neoplasm involving the breast. "Elevated expression of PREX1 has been associated with the development of melanoma, prostate cancer, and breast cancer." (PMID 34783629, 2021). "P-Rex1 up-regulation in luminal breast cancer has been associated with deregulated epigenetic mechanisms that lead to PREX1 gene promoter demethylation." (PMID 29983884, 2018). "Increased P-Rex1 expression in ER positive (luminal) breast tumors was associated with hypomethylation of the PREX1 promotor, while hypermethylation was observed in basal-like breast cancers." (PMID 28698809, 2017). "Taken together, these findings support the concept that the methylation status of the PREX1 promoter is causally linked to P-REX1 upregulation and associates with poor outcome of breast cancer patients, thus implying PREX1 methylation as a prognostic factor." (PMID 25248717, 2014). "It is conceivable that derepression of P-REX1 expression in luminal breast cancer is associated with demethylation of the PREX1 promoter." (PMID 25248717, 2014). "Our results identified methylation of the PREX1 gene promoter as a key mechanism implicated in the differential expression of P-REX1 in breast cancer." (PMID 25248717, 2014). "We therefore asked if methylation of the PREX1 promoter is linked to survival in patients with breast cancer." (PMID 25248717, 2014). "Increased expression of P-REX1 in luminal breast cancer is associated with demethylation of CpG islands in the PREX1 promoter." (PMID 25248717, 2014). "Low PREX1 methylation associates with elevated risk of breast cancer mortality." (PMID 25248717, 2014). "Evidence suggested that Rac and PREX1 protein are increased in cell proliferation and migration in several human cancers such as melanoma, breast cancer, prostate cancer, and oral squamous cell carcinoma." (PMID 33652974, 2021). "We and others recently proposed that the protein phosphatidylinositol-3,4,5-trisphosphate-dependent Rac exchange factor 1 (P-Rex1) is a potential breast cancer biomarker to predict sensitivity to therapeutic inhibitors of phosphatidylinositol 3-kinase (PI3K)." (PMID 28698809, 2017). "Levels of PREX1 have been reported to be regulated by promoter histone acetylation in prostate cancer and by subtype-specific promoter methylation in breast cancer." (PMID 28051998, 2017). "In breast cancer, PREX1 promotes breast cancer metastasis, and also tumour growth, in mouse xenografts." (PMID 28051998, 2017). "Luminal A breast cancer patients with high PREX1 levels from which follow-up data was available were divided into two groups, low MMP10 and high MMP10 levels, based on the median expression values." (PMID 27351228, 2016). "Consistent with our previous immunohistochemistry and bioinformatics analyses, RNA-seq expression data revealed higher PREX1 levels in luminal breast cancer specimens relative to normal samples from the same patients (p = 7.15e–11, n = 168)." (PMID 27351228, 2016). "Next, we analyzed the methylation status of PREX1 in 51 breast cancer cell lines obtained from the Infinium HumanMethylation27 BeadChip array (Illumina; San Diego, CA, USA); GSE42944)." (PMID 25248717, 2014). "A comprehensive analysis of human mammary cell lines and patient-derived tumors revealed marked differences in PREX1 promoter methylation in distinct breast cancer subtypes that inversely correlate with P-REX1 expression levels." (PMID 25248717, 2014). "Toward the goal of dissecting the mechanistic basis of P-REX1 overexpression in breast cancer, in this study we focused on the analysis of methylation of the PREX1 gene promoter." (PMID 25248717, 2014). "A comprehensive analysis of human breast cancer cell lines and tumors revealed significant hypomethylation of the PREX1 promoter in ER-positive, luminal subtype, whereas hypermethylation occurs in basal-like breast cancer." (PMID 25248717, 2014).
breast cancer (continued). "Following the studies in mammary cell lines, we next examined PREX1 gene methylation in human breast cancer specimens using the TCGA public database." (PMID 25248717, 2014). "Towards the goal of dissecting the mechanistic basis of P-REX1 overexpression in breast cancer, in this study we focused on the analysis of methylation of the PREX1 gene promoter." (PMID 25248717, 2014). "PREX1 gene methylation in different human breast cancer subtypes was analyzed from the TCGA database." (PMID 25248717, 2014). "PREX1, CPNE1, and SAMD12 have, respectively, fused with other genes in breast cancer cell-lines: NFS1-PREX1 in SK-BR-3, CPNE1-PI3 in BT-474, and PHF20L1-SAMD12 in HCC1954." (PMID 23972288, 2013). "In 2016, Liu et al16 found that the activity of PREX1-Rac-GEF is crucial for the growth of cells dependent on Prex1 and the growth of transplanted tumors, and it may become a therapeutic target for breast cancer." (PMID 37434402, 2023). "In addition, high expression of PREX1 correlates with decreased disease-free survival in breast cancer patients." (PMID 28051998, 2017). "P-Rex1 overexpression only occurs in a subset of human breast cancers, namely luminal A and B subtypes, which may be the consequence of altered epigenetic regulatory mechanisms that result in demethylation of the PREX1 gene promoter." (PMID 27351228, 2016). "The significant association between PREX1 and MMP10 expression in luminal tumors, together with the poor prognosis found in luminal breast cancer patients with high PREX1 and MMP10 expression, suggest a causal relationship with disease progression that deserves to be fully explored." (PMID 27351228, 2016). "The P-REX1/Rac pathway plays an important role in ErbB receptor-driven breast cancer cell motility and invasiveness, and consequently the methylation status of the PREX1 promoter could be a determinant in the progression of subsets of breast cancer patients." (PMID 25248717, 2014). "Interestingly, several other HDAC1/7-SE upregulated targets, such as SNPH, CCANG4, PREX1, IGFBP5, IL34 and BCAS4 also demonstrate remarkable level of breast cancer associated over-expression, providing additional support for the relevance of the ET-125 signature." (PMID 36038558, 2022). "Therefore, survival correlations with P-REX1 expression most likely include luminal breast cancer patients as the largest population, thus arguing the possibility that PREX1 promoter methylation has prognostic value to predict outcome in this subset of patients." (PMID 25248717, 2014). "Furthermore, both PREX1 and MTBP have been previously implicated in breast cancer progression." (PMID 23972288, 2013). "The inverse correlation found between PREX1 promoter methylation and P-REX1 expression strongly indicates a role for this epigenetic mechanism in regulating the P-REX1-Rac signaling pathway in breast cancer cells through the control of P-REX1 expression." (PMID 25248717, 2014). "On the other hand, a similar analysis carried out in basal breast cancer specimens revealed that PREX1 levels were not significantly different (p > 0.05, n = 36) between cancer and normal tissue, which is consistent with our previous study." (PMID 27351228, 2016). "With respect to this, a major link may be represented by PREX1 (RAC-exchanger-factor-1), an important determinant of the sensitivity of breast cancer cells to PI3K inhibitors." (PMID 25888236, 2015). "We found that the human PREX1 gene promoter has a CpG island located between -1.2 kb and +1.4 kb, and that DNA methylation in this region inversely correlates with P-REX1 expression in human breast cancer cell lines." (PMID 25248717, 2014). "At the present time, we do not know if demethylation of the PREX1 promoter is a consequence of global aberrant hypomethylation as reported in breast cancer or whether it is dictated by a specific signal." (PMID 25248717, 2014).
melanoma (20 papers, 2014 to 2025). A malignant, usually aggressive tumor composed of atypical, neoplastic melanocytes. "Although overexpression in melanoma can elicit invasion and metastasis, PREX1 is rarely mutated in human cancer." (PMID 39636745, 2025). "Next, to both validate response data and develop a more tractable in vitro system to understand the role of PREX2 under treatment, we used CRISPR/Cas9-mediated gene editing to disrupt the expression of PREX2 or its close relative PREX1 in the PTEN-deficient WM266.4 melanoma line." (PMID 39636745, 2025). "In mouse models, deletion of the PREX1 gene leads to reduced Rac1 activity and metastasis in melanoma." (PMID 38191532, 2024). "Upregulation of PREX1 expression occurs in many types of cancers, particularly in breast and prostate cancers and in melanoma." (PMID 30941304, 2019). "The potential importance of RAC1 function in melanoma is further underlined by the discovery of frequent alterations in PREX2, and to a lesser extent PREX1, which are guanine nucleotide exchange factors for RAC1." (PMID 31257073, 2019). "Deregulation of the PREX1 gene is common in several types of human cancers, including melanoma, breast and prostate cancer, with overexpressed P-Rex1 promoting tumor growth and/or metastasis." (PMID 26792863, 2016). "Additionally, deletion of Prex1 in the Tyr:NrasQ61K;INK4a−/− melanoma mouse model results in the development of less metastasis to the lung than controls." (PMID 34503171, 2021). "However, deletion of Prex1, encoding an upstream activator of RAC1, has been reported to suppress migration and metastasis in a melanoma model." (PMID 31257073, 2019). "Overall, 30% of melanomas show alterations in either PREX1 or PREX2, although the functional significance of most of these individual changes has not been tested and may not all be mediated through RAC1 signaling." (PMID 31257073, 2019). "Mutations in the RhoGEF PREX2 were identified in melanoma patients, and expression of mutated PREX2 proteins in melanoma cells accelerates tumor growth following their grafting in mice Moreover, deletion of Prex1 expression prevents melanocyte migration during mice development." (PMID 34503171, 2021). "Ultimately, the ERK-MAPK pathway leads to overexpression of PREX1, subsequently activating RAC, thereby enabling the invasive capability of melanoma cells." (PMID 40072059, 2025). "In human melanoma cells, the guanine-nucleotide exchange factor (GEF) PREX1, an activator of Rho GTPases, plays a crucial role in facilitating cell invasion." (PMID 40072059, 2025). "Among the pro-metastatic Rac-GEFs, Phosphatidylinositol-3,4,5-Trisphosphate Dependent Rac Exchange Factor 1 (PREX1) has been found to be highly expressed in many types of tumors, including melanoma, breast, prostate cancer and others." (PMID 38191532, 2024). "We have demonstrated that the RAC1-GEF PREX1 plays critical roles in melanoblast migration during early murine embryonic development, melanoma cell invasion and migration, and metastasis in a patient-relevant preclinical model of NRAS-mutant melanoma." (PMID 39636745, 2025).
prostate carcinoma (15 papers, 2014 to 2024). A carcinoma that arises from epithelial cells of the prostate gland. "Overexpression of PREX1 has been linked to increased migration and metastases in melanoma and prostate cancer." (PMID 28051998, 2017). "In prostate cancer, NRP2, mediates bevacizumab resistance via a VEGF/NRP2/PREX1/RAC1 pathway." (PMID 35875157, 2022).
glioblastoma (7 papers, 2017 to 2021). The most malignant astrocytic tumor (WHO grade IV). "PREX1 promotes the motility and invasion of glioblastoma cells, promoting Rac-mediated activation of p21-associated kinases and atypical PKC, which have established roles in cell motility." (PMID 28051998, 2017). "For comparison, PREX1-null cells were generated in glioblastoma cells from a second patient, PriGO9A cells." (PMID 34624316, 2021). "To determine if PREX1-null glioblastoma cells had lost their multilineage potential, we treated them with BMP4." (PMID 34624316, 2021). "This second mechanism for Lgl1 phosphorylation is probably active in only a small subset of glioblastoma patients, based on analysis of exon expression levels and comparative RNA-seq expression of PREX1 and TIAM1 mRNA in 152 patients in the TCGA database." (PMID 34624316, 2021). "We used CRISPR/Cas9 to knockout PREX1, a PI 3-kinase pathway-responsive Rac guanine nucleotide exchange factor, in patient-derived glioblastoma cells." (PMID 34624316, 2021). "We initially focused on the Rac GEF PREX1, which we previously showed was overexpressed in glioblastoma relative to normal brain." (PMID 34624316, 2021). "CRISPR/Cas9 knockout of PREX1 in glioblastoma cells from one patient showed markedly reduced Lgl1 phosphorylation, along with reduced motility and an apparent partial differentiation along the neuronal lineage." (PMID 34624316, 2021). "Prex1, a guanine nucleotide exchange factor, is predictive of shorter glioblastoma patient survival when its expression is increased." (PMID 32309604, 2018). "PREX1 was required for glioblastoma cell invasion in the three glioblastoma cell cultures with a predominantly classical subtype expression signature." (PMID 28051998, 2017). "There are several important consequences regarding the use of PREX1 as a GEF for Rac in glioblastoma." (PMID 28051998, 2017). "PREX1 expression varied across primary glioblastoma cell cultures from different patients, with the highest expression in PriGO7A cells and the lowest expression in PriGO17A cells." (PMID 28051998, 2017). "We show that PREX1 is expressed in glioblastoma cells isolated under serum-free conditions and in patient biopsies." (PMID 28051998, 2017). "Consistent with current knowledge on the activation of PREX1, glioblastoma invasion requires input from both PI 3-kinase signalling and G protein-coupled receptor signalling." (PMID 28051998, 2017). "PREX1 therefore has a general role in glioblastoma invasion, although it is possible that some glioblastomas use an alternate mechanism." (PMID 28051998, 2017). "Intracranial growths of primary glioblastoma cultures showed a uniform expression pattern of PREX1 with the intensity of signal proportional to the Western blot intensities across the PriGO7A, 8A and 9A cell cultures." (PMID 28051998, 2017). "Thus PREX1 promotes Lgl1 phosphorylation in glioblastoma by virtue of its high expression in glioblastoma compared with other Rac GEFs along with its responsiveness to PI 3-kinase pathway signaling, rather than as a consequence of unique scaffolding functions." (PMID 34624316, 2021). "We used CRISPR/Cas9 to knockout PREX1 in PriGO8A glioblastoma cells." (PMID 34624316, 2021). "PREX1-null glioblastoma cells have reduced motility, as expected based on our earlier study." (PMID 34624316, 2021). "As in other cancers, PREX1 promotes motility and invasion in glioblastoma cells." (PMID 28051998, 2017). "For tumor tissue, ninety-one percent of glioblastoma cases showed some level of PREX1 expression." (PMID 28051998, 2017). "We show here that PREX1 is overexpressed in many glioblastomas." (PMID 28051998, 2017). "PREX1 expression was examined by Western blotting in total cell lysates from glioblastoma cells isolated from patients under serum-free conditions (hereafter referred to as primary glioblastoma cells or PriGO cells)." (PMID 28051998, 2017). "This study shows that PREX1 is overexpressed in many glioblastomas." (PMID 28051998, 2017).